ALDH3A2 (aldehyde dehydrogenase 3 family member A2)
Diseases named in the same sentence as ALDH3A2 in open-access papers (continued):
Sharing a sentence is not in itself a finding about the gene and the disease.
Infertility (1 paper, 2019). "A direct correlation between aging and OS increase has been reported with aging-related decay of fertility, and our laboratory reported an increased expression levels of the oxidative stress response gene ALDH3A2 in granulosa-lutein cells that is related to age and infertility diagnosis." (PMID 31906251, 2019).
melanoma (1 paper, 2024). A malignant, usually aggressive tumor composed of atypical, neoplastic melanocytes. "Taken together, ALDH2, ADH1B, ALDH3A2, DPT, EPHX2, and GATM are potential biomarkers of melanoma, which have high prediction values for melanoma." (PMID 38378847, 2024). "After literature research, we chose 6 hub genes: ALDH2, ADH1B, ALDH3A2, DPT, EPHX2, and GATM, which were rarely reported in melanoma as the object of this research to explore their accuracy in the diagnosis and prediction of melanoma." (PMID 38378847, 2024).
metastatic tumors (1 paper, 2012). "The expression of ALDH2 and ALDH3A2 were significantly down-regulated in primary tumor samples and further down-regulated in metastatic tumors, similar to AOX1 expression." (PMID 23119026, 2012).
microcephaly (1 paper, 2024). A congenital or acquired developmental disorder in which the circumference of the head is smaller than normal for the person's age and sex. "In contrast, Mcph1 (microcephaly, primary autosomal recessive 1, ΔREC = −3515%), involved in determining the mitral valve diameter and DNA-damage signaling and repair, and Aldh3a2 (ΔREC = −1559%) had the largest reduction in the expression control." (PMID 38534766, 2024).
Pancreatic Cancer (1 paper, 2017). "HIPK3 has been related to apoptosis resistance, CBR1 has been identified as a patient survival marker, ALDH3A1 and ALDH3A2 have been related to drug response, and NOS1 has been related to pancreatic cancer risk." (PMID 29285214, 2017).
peritoneal disease (1 paper, 2020). "The number of sites with peritoneal disease was correlated with increased levels of ALDH3A2 (p = 0.03, τ = 0.36) and CRIP2 (p = 0.01, τ = 0.378)." (PMID 32253542, 2020).
thyroid cancer (1 paper, 2025). "Similarly, ALDH1A1, alongside other aldehyde dehydrogenase family members such as ALDH4A1 and ALDH3A2, underscores the role of metabolic dysregulation in thyroid cancer progression." (PMID 40861812, 2025).
van der Woude syndrome (1 paper, 2019). Van der Woude syndrome (VWS) is a rare congenital genetic dysmorphic syndrome characterized by paramedian lower-lip fistulae, cleft lip with or without cleft palate, or isolated cleft palate. "ALDH3A2 (aldehyde dehydrogenase 3 family member A2), a membrane-associated protein, and SPECC1L are implicated in craniofacial disorders (e.g., Van Der Woude syndrome) in humans." (PMID 30689847, 2019).
tumor (29 papers, 2012 to 2026). "Correspondingly, tumor-associated target genes including ALDH3A2, SEMA3F, MAP4K5, and TRIP13 were upregulated, whereas PIK3IP1, AGO2, MMP2, and RALBP1 were suppressed." (PMID 41897301, 2026). "Metabolic genes CYP1B1, AANAT, ADH5, and ALDH3A2, associated with the serotonin and melatonin biosynthesis pathway, contribute to tumour growth, immune modulation, and altered metabolic states in the TME." (PMID 39457550, 2024). "With a median follow up of 3.78 years for GSE32603 and 2.74 years for GSE25066, we found a significantly lower risk of tumor recurrence in patients with high expression of ALDH3A2 in the primary tumor compared with those having tumors with low expression of ALDH3A2 in both databases." (PMID 35515127, 2022). "Specifically, we integrated the DEGs between ALDH3A2-high and -low groups from the TCGA dataset with macrophage polarization-related genes from the GeneCards database and tumor microenvironment (TME)-related genes from the TISIDB database." (PMID 41444219, 2025). "Conversely, overexpression of ALDH3A2 in GC cell lines significantly alleviates the aggressive progression of GC cells, suppressing both tumor growth in the xenograft mouse model." (PMID 41444219, 2025). "Compared with normal renal tissue, ALDH3A2 expression is significantly downregulated in ccRCC tissue, where it functions to inhibit tumor progression by modulating the PI3K-AKT pathway." (PMID 41444219, 2025). "In this study, we reveal that ALDH3A2-induced ferroptosis in GC cells not only suppresses GC tumor progression but also contributes to the reprogramming of the tumor immune microenvironment." (PMID 41444219, 2025). "In Group 4, almost all the connections become activating except for Aldh3a2 and Eno2; which were found to be strongly downregulated in all the tumor subgroups confirming their role in cancer resistance." (PMID 37016281, 2023). "We found that high expression of ALDH3A2 was associated with a lower risk of tumor recurrence in patients received NAC, including those achieved a tumor pCR." (PMID 35515127, 2022). "Clinical T stage, clinical N stage and tumor expression of ALDH3A2 were potential markers for predicting tumor recurrence in the pCR patients after NAC." (PMID 35515127, 2022). "The results showed that the mRNA expressions of ALDH1A3, ALDH1L2, ALDH2, and ALDH3A2 were obviously related to tumor purity." (PMID 34928471, 2022). "To verify the prognostic value of ALDH3A2 tumor expression, we performed survival analyses on ALDH3A2 using two publicly available independent datasets from the GEO database (GSE32603 and GSE25066)." (PMID 35515127, 2022). "ALDH3A2 had little effect on the clinical characteristics; only the grade of the tumor showed a significant correlation." (PMID 33148208, 2020). "The “CIBERSORT” package in R software and TIMER website was used to investigate the relationship between ALDH3A2 and tumor immunity." (PMID 33148208, 2020). "The most significantly downregulated gene in tumor tissue was ALDH3A2 (OR 0.03, p = 3.23 × 10−12) annotated with the KEGG glycolysis and fatty acid metabolism pathways." (PMID 27980733, 2016). "Furthermore, ALDH3A2-induced ferroptosis promotes an anti-tumor immune microenvironment via M1 macrophage polarization and IL-1β-mediated PD-L1 downregulation." (PMID 41444219, 2025). "Similarly, tumor volume and weight were significantly reduced in mice injected with ALDH3A2-overexpressing cells compared to control mice, demonstrating that ALDH3A2 overexpression effectively suppresses GC tumor growth in vivo." (PMID 41444219, 2025). "Our findings indicated that the tumor suppressor SDHC could repress fatty acid synthesis by decreasing the expression of ALDH3A2 and simultaneously promote FAO by upregulating the FAO-related enzymes ACOX1 and CPT1A through the PI3K/AKT signaling axes." (PMID 38844980, 2024). "Together, these findings potentially indicate a tumor suppressor role of ALDH3A2 in solid tumors." (PMID 35515127, 2022).
tumor (continued). "The AGL and ALDH3A2 were all significantly downregulated in the tumor tissues." (PMID 33391344, 2020). "Moreover, we provide robust in vivo evidence demonstrating that targeting ALDH3A2, either through genistein treatment or gene overexpression, effectively inhibits GC cell proliferation, migration, and invasion, while suppressing tumor growth and metastasis by promoting ferroptosis." (PMID 41444219, 2025). "Additionally, low expression of ALDH3A2 was associated with a higher risk of tumor recurrence in the non-pCR patients." (PMID 35515127, 2022). "Interestingly, we found that ALDH3A2 co-expression might be negatively correlated with the PDCD1, PDCD1LG2, and CTLA4 genes, and positively associated with tumor purity." (PMID 33148208, 2020). "The genes EZH2 was significantly higher expressed in tumor tissue while SCP2, ALDH3A2, and PRKAA2 were significantly upregulated in normal tissue." (PMID 40271062, 2025). "ALDH2, ADH1B, ALDH3A2, DPT, EPHX2, and GATM were down-regulated in the tumor tissues, which is consistent with the expression of hub genes in the GSE3189 and GSE46517 datasets." (PMID 38378847, 2024). "The expressions of ALDH3A2 and MAOA were significantly lower in STAD tumor tissues than those in the paired adjacent normal tissues, respectively (all P < 0.05)." (PMID 36915111, 2023). "Higher expressions of NOX4 and FKBP10, and lower expressions of ALDH3A2 and MAOA were observed in tumor samples compared with the normal tissues, respectively." (PMID 36915111, 2023). "Clinical samples showed significant downregulation of the following genes: CPT2, ACAA2, HPGD and ALDH3A2, while the expression of ENO2, TDO2, CPOX, ACADL and PTPRG was significantly upregulated in the tumor tissue (p < 0.01)." (PMID 36230866, 2022). "We found that plasma circ-CYP24A1, circ-ALDH3A2 and circ-DNA2 levels displayed correlations to maximum tumor diameter, tumor thickness, preoperative serum SCC-Ag and serum SCC-Ag 1 month after surgery." (PMID 34109199, 2021). "The violin plot based on TCGA data displayed remarkably different expression levels of ALDH3A2, B3GAT3, and CPT2 in tumor group compared with that of the normal group." (PMID 33194661, 2020). "Of note, we demonstrate that ALDH3A2 suppresses the proliferation, migration, and invasion of GC cells by promoting ferroptosis in a GPX4-dependent manner, thereby suppressing aggressive tumor progression." (PMID 41444219, 2025). "Conversely, SCP2, ALDH3A2, and PRKAA2 were found to be expressed at lower levels in tumor tissues." (PMID 40271062, 2025). "The associations between the tumor purity and these 12 immune-survival-related genes were analyzed; the results revealed that four genes, i.e., FAM134B, ALDH3A2, SAV1, and RORC were positively related to tumor purity, and one gene (FN1) was negatively related to tumor purity." (PMID 35893817, 2022). "The elevated expressions of FAM134B; ALDH3A2; RORC; and SAV1 were related to superior MESO’s OS, indicating that only four tumor antigens could be assumed to stimulate the immune system." (PMID 35893817, 2022). "We used qPCR to analyze the ALDH3A2, PDCD1, PDCD1LG2, and CTLA-4 mRNA expression levels in 52 tumor tissues, which indicated a negative spatial correlation between ALDH3A2 and PDCD1 (R2 = 0.3576), PDCD1LG2 (R2 = 0.3878), and CTLA-4 (R2 = 0.2556)." (PMID 33148208, 2020). "For example, ALDH1A2, ALDH2, ALDH3A2 and ALDH9A1 were downregulated in all tumors among the 5 cancer types, whereas ALDH1B1, ALDH1L2 and ALDH18A1 were most upregulated in tumor parts." (PMID 29426835, 2018).
tumor (continued). "Furthermore, the conditioned medium from these M1-polarized macrophages significantly suppressed the expression of PD-L1, a key factor of immunosuppressive tumor microenvironment, which can be prevented by depleting IL-1β in macrophages (CM-THP1-shIL1β-CM-GC-EF1a-ALDH3A2)." (PMID 41444219, 2025). "Additionally, in vitro analyses of GC cell lines (MGC803, HGC27, SGC7901, and MKN45) revealed significantly reduced ALDH3A2 mRNA and protein levels compared with the normal gastric epithelial cell line GES-1, suggesting a potential tumor-suppressive role of ALDH3A2 in contributing to GC progression." (PMID 41444219, 2025). "The analysis further revealed a total of tumor antigens including FAM134B, ALDH3A2, SAV1, RORC, and FN1, which were considered as significant candidates for the MESO-mRNA vaccine that could have immune provocative effects and be both presented and processed by APCs for a tumor response induction." (PMID 35893817, 2022).
cancer (15 papers, 2017 to 2025). A tumor composed of atypical neoplastic, often pleomorphic cells that invade other tissues. "However, in transcriptomic data, ALDH3A2 expression was most highly correlated with telomeric neighbors, and an analysis of ALDH3A2 expression in The Cancer Cell Line Encyclopedia dataset showed a positive correlation with copy number." (PMID 33674602, 2021). "While there is no literature linking the influence of aldehyde dehydrogenases on oxidative phosphorylation in AD, there is evidence of their interdependence from the cancer literature, supporting the hypothesis that ALDH3A2 may directly modulate the ETC in AD pathogenesis as well." (PMID 41279371, 2025). "The isoforms aldehyde dehydrogenase 1 family member A2 (ALDH1A2), 2 family member (ALDH2), ALDH3A2, and 9 family member A1 (ALDH9A1) were downregulated in all cancers studied." (PMID 40923024, 2025). "In detail, ALDH9H1, ALDH18A1, ALDH3A2, ALDH1A1, ALDH1B1 and ALDH2 were expressed higher than other ALDH family genes in all cancers." (PMID 34670872, 2021). "It is noteworthy that some isoforms, such as ALDH2, ALDH3A2, ALDH3B1, and ALDH5A1, are expressed at similar levels across cancer types." (PMID 30220009, 2019). "Unlike ALDH3A2, aldehyde dehydrogenase 1 family member A1 (ALDH1A1), 1 family member B1 (ALDH1B1), and 3 family member A1 (ALDH3A1) expression levels are elevated in other malignant tumors and associated with poorer survival outcomes." (PMID 40923024, 2025).
neurodegenerative disease (2 papers, 2021 to 2026). A disorder of the central nervous system characterized by gradual and progressive loss of neural tissue and neurologic function. "Restoring the UBQLN2-ILVBL/ALDH3A2 axis attenuates neurodegenerative phenotypes in neurons, organoids and mice, establishing UBQLN2 as a critical regulator of metabolic homeostasis in ALS/FTD and other related neurodegenerative diseases." (PMID 41912662, 2026).
neurological diseases (2 papers, 2021 to 2023). "The regions of the 3 CNVs are located in chromosome Xp22.31, 15q11.2–13.1 and 17p11.2, and harbored genes associated with neurological diseases including GABRB3, UBE3A, MAGEL2, RAI1, ALDH3A2, ATPAF2 according to the database of Online Mendelian Inheritance in Man (OMIM)." (PMID 33753861, 2021).
ALDH3A2 also shares sentences with these, for which no sentence is quoted: Intellectual disability (4 papers); metabolic disorder (3); neurocutaneous disorder (3); spastic diplegia (3); atherosclerosis (2); gastric adenocarcinoma (2); genetic disorder (2); Alzheimer disease (1); autosomal recessive congenital ichthyosis (1); cardiac disease (1); Chanarin–Dorfman syndrome (1); Cognitive impairment (1); colorectal cancer (1); congenital ichthyosis (1); dementia (1); developmental delay (1); diabetic nephropathy (1); Dry skin (1); gastric tumors (1); head and neck cancer (1); hereditary spastic paraplegia (1); Huntington disease (1); Hyperammonemia (1); hyperlipidemia (1); hyperprolinemia (1); hyperprolinemia type 2 (1); infection (1); Lipid storage disease (1); lung squamous cell carcinoma (1); Methylmalonic aciduria (1).
A further 16 diseases each share a sentence with ALDH3A2 in 1 paper.